CT47A12 (cancer/testis antigen family 47 member A12)
Synonyms: CT47; CT47.12
Gene: Protein-coding gene on chromosome X (120,930,250 to 120,932,301, reverse strand). Ensembl gene ENSG00000226685.
Subcellular location (Human Protein Atlas): Nucleoli
Homologues: Orthologues: macaque CT47B1 (77% identical). Paralogues in human: CT47A1 (100% identical), CT47A10 (100% identical), CT47A11 (100% identical), CT47A2 (100% identical), CT47A3 (100% identical), CT47A4 (100% identical), CT47A5 (100% identical), CT47A6 (100% identical), CT47A7 (100% identical), CT47A8 (100% identical), CT47A9 (100% identical), CT47B1 (86% identical), and 1 more.